ANGPT2 (angiopoietin 2)
Diseases named in the same sentence as ANGPT2 in open-access papers (continued):
Sharing a sentence is not in itself a finding about the gene and the disease.
cancer (continued). "VEGF proteins were particularly abundant in all cancer and endothelial cell secretomes, whereas ANG and ANGPT2/ANGPTL4 in SK-OV-3, suggesting a potentially significant role in the formation of the HBEC-5i/SK-OV-3 networked constructs." (PMID 41279931, 2025). "In GC cells, ANGPT2 was shown to encourage growth, invasion, and EMT progression 65, and similar phenomena were also observed in lung 66 and breast 67 cancers." (PMID 39309430, 2024). "In cancer, pathological angiogenesis is mediated by the vascular endothelial growth factor A (VEGFA) and angiopoietin-2 (ANGPT2), which both constitute good targets of anti-angiogenic therapies." (PMID 38903504, 2024). "Increased ANGPT2/ANGPT1 ratio at the mRNA level has been reported to correlate with neo‐angiogenesis and poor prognosis in many cancer types." (PMID 35266635, 2022). "In cancer, the most relevant markers involved in anti-VEGF resistance are angiopoietin-2 (Ang2), fibroblast growth factor 2, IL-1, platelet-derived endothelial cell growth factor and TGF-β." (PMID 36556139, 2022). "As a result, one of the pillars of anti-cancer therapy is based on counteracting pro-angiogenic factors such as Vascular Endothelial Growth Factor A (VEGF-A), angiopoietin 2 (Ang-2) and Delta-like Ligand 4 (DLL4)." (PMID 36432631, 2022). "It has been previously reported that Angiopoietin-2 (Ang2) and STAT3 are involved in pejorative clinical outcomes in cancer patients." (PMID 34359795, 2021). "The baseline level of plasma angiopoietin-2 was median 1261.8 pg/mL (IQR 1018.6–1579.6, range 967.5–1802.1) in stage III and IV cancer and 987.9 pg/mL (IQR 883.9–1303.8, range 813.7–1499.1) in stage I and II cancer (Mann-Whitney U test, p = 0.2556)." (PMID 32799882, 2020). "ANGPT2, FLT1, and ESM1 are pro-angiogenic genes, with ANGPT2 and FLT1 playing a role in enhancing sprouting angiogenesis, and ESM1being upregulated in hypervascularised cancers." (PMID 31665941, 2019). "Here, we showed that ADAM9 also contributes the functions of angiogenesis and vascular remodeling for cancer progression through regulation of VEGFA, ANGPT2, and PLAT via in vitro and in vivo experiments." (PMID 29118335, 2017). "In NSCLC, cancer cells secrete high amounts of proinflammatory and proangiogenic chemokines, such as VEGF, angiopoietin-2, and IL-8, promoting the proliferation and migration in vascular endothelial cells." (PMID 27806334, 2016). "Upregulation of angiogenic factors such as VEGF, VEGFR2, and angiopoietin-2 via the thrombin/PAR-dependent pathway together with enhanced barrier permeability of ECs results in the induction of angiogenesis and cancer dissemination." (PMID 26573921, 2015). "Our data demonstrate in malignant tumours a significantly higher expression of VEGF, ANGPT2 and EFNB2 at both, gene and protein levels, in malignant tumours when compared to normal oral mucosa." (PMID 26044849, 2015). "In addition, angiopoietin-2 (ANGPT2) was highly correlated with ESM1 and interplayed with Akt to induce the EMT and cancer progression in GC." (PMID 39309430, 2024). "Additionally, angiopoietin-2 (ANGPT2) was found to be highly correlated with ESM1 and interplayed with Akt to induce the EMT and cancer progression." (PMID 39309430, 2024). "We identified ANGPT2 (logFC 3.9, FDR 2.00 × 10−4), APOA1(logFC −4.4, FDR 0.0067), FOS (logFC 1.4, FDR 0.0059) and VEGFA (z-score 2.228, overlap p-value 6.45 × 10−3) as the molecules of interest that have biomarker applications in various cancers." (PMID 35052372, 2021). "Moreover, the set of two markers, TGF-β1 and angiopoietin-2, provided effective prognoses in CCA patients with metastasis and severe cancer stage conditions." (PMID 33806004, 2021). "Moreover, ANGPT2 and PDGF are also relevant molecules for cancer-cell-survival in the bone marrow niche for ER+ breast and PCa cells, respectively." (PMID 34944822, 2021).
cancer (continued). "In addition, upon adhesion of cancer cells to endothelial cells they secrete cytokines and growth factors, such as VEGF, angiopoietin 2 (Angpt2), and angiopoietin-like 4 (Angptl4), leading to hyperpermeability of the endothelial wall." (PMID 33747899, 2020). "In our study, results showed that MAGEA3 did not upregulate the expression of PDGF, FGF, and ANGPT2 but could lower glycolysis and respiration levels in cancer cells." (PMID 40342736, 2025).
infection (18 papers, 2010 to 2025). The state of being infected such as from the introduction of a foreign agent such as serum, vaccine, antigenic substance or organism. "As an antagonistic gene of Angpt1, the mRNA level of Angpt2 was significantly down-regulated at 10–12 weeks post-infection, indicating elevated angiogenesis." (PMID 41334166, 2025). "We found that in first infection Angiopoietin-2 levels increased by more than an order of magnitude but in second infection – with an identical parasite burden – levels did not deviate from a healthy uninfected baseline." (PMID 33752799, 2021). "Dramatic release of Angpt2 to BAL was observed during lung injury stage of infection, with marked attenuation of released levels by the original and primed ASC-CS." (PMID 33804896, 2021). "Frozen plasma from 410 children presenting to the Jinja Regional Hospital in Uganda with suspected infection was used to measure biomarkers of endothelial (Angiopoietin-2, sFlt-1, sVCAM-1, sICAM-1) and immune (IL-6, IP-10, sTNFR-1, CHI3L1) activation." (PMID 28419100, 2017). "Patients with severe CRS are mainly characterized by elevated serum levels of angiopoietin 2 (ANGPT2) and von Willebrand factor (VWF), and these can also be used to distinguish CRS from infection." (PMID 38923216, 2024). "Similar to Angpt2 BAL levels, PDL1 levels in lung and BAL were dramatically increased in response to the infection and decreased in response to the ASC secretome administration." (PMID 33804896, 2021). "Unlike what was observed for inflammatory cytokine content, soluble proangiogenic factors assayed (FGF-2, HGF, and ANGPT-2) were constitutively expressed in the UI corneas and did not change as a result of VEH or AP20187 treatment following infection." (PMID 28903153, 2017).
cardiovascular disease (10 papers, 2013 to 2025). "For LVEF, proteins previously associated with cardiovascular disease that were among the strongest associations included atrial natriuretic factor (ANP) and angiopoietin-2." (PMID 38597740, 2024). "Angiogenesis is involved in cardiovascular diseases and this process requires a complex cross-talk between numerous cell types and growth factors, among which ANGPT2 provides a possible link between blood vessel formation and inflammation." (PMID 35004874, 2021). "The roles of ANGPT2 in cardiovascular disease may be context-dependent." (PMID 35004874, 2021). "Thus, angiopoietin-2 is a marker for cardiovascular disease in children on chronic dialysis and may act as an anti-angiogenic and pro-inflammatory effector in this context." (PMID 23409162, 2013). "The HIF-1 signaling pathway is closely related to hypoxia–ischemia in cardiovascular diseases, and we found four genes (FLT1, KDR, ANGPT2, and PGF) related to angiogenesis in the pathway." (PMID 36435742, 2022). "In cardiovascular diseases, blood vessel leakage is induced by the inhibition of TIE2, mediated by ANGPT2." (PMID 36397962, 2022). "We found that ANGPT2, PLAT (tPA), SERPINE1 (PAI-1), and VEGFA, which are involved in cardiovascular disease, were influenced in ADAM9 knockdown cells." (PMID 29118335, 2017). "In T2DM patients, a study showed that serum ANGPT-2 levels were higher in patients with cardiovascular disease (CVD) compared to those without CVD or healthy controls." (PMID 34762787, 2021).
kidney disease (9 papers, 2018 to 2025). "The other markers that indicate the early progression of kidney diseases are neutrophil gelatinase associated lipocalin and angiopoietin-2." (PMID 31888083, 2019). "We also identified genes previously linked to kidney disease, such as fatty acid binding protein 4 (FABP4, log2FC = 5.69), trefoil factor 3 (TFF3, log2FC = 5.58), and angiopoietin 2 (ANGPT2, log2FC = 2.46)." (PMID 40663403, 2025).
bacterial infection (4 papers, 2016 to 2024). "Specifically, this bacterial infection induces the expression of Angpt2, Tnf-A and VegfA at the mRNA and protein levels." (PMID 36874142, 2023).
vascular disorder (4 papers, 2023 to 2025). A general term used to describe any disease affecting blood vessels]. "We hypothesise that high angiopoietin-2 levels might reflect the vasculopathy and disturbed angiogenesis that is observed by nailfold capillaroscopy (abnormal nailfold capillaries with capillary giants, haemorrhages and abnormal capillary morphology)." (PMID 39242108, 2024).
cardiac disease (2 papers, 2022). "Future studies on whether ANGPT2 may predict cardiac disease, and whether regulation of ANGPT2 expression may have a therapeutic potential, are in demand." (PMID 35304587, 2022).
myopathy (2 papers, 2021 to 2026). A disease of the muscle in which the muscle fibers do not function properly. "Angiopoeitin 2 (ANGPT2) exhibited the highest predicted activation Z-score of all molecules in the WB dataset, suggesting that the proteomic landscape of WB myopathy would promote vascularization." (PMID 33419207, 2021).
gastrointestinal tumors (1 paper, 2022). "More importantly, we found that the clinical relevance of MYBL1 and ANGPT2 was further confirmed in multiple gastrointestinal tumors." (PMID 35987690, 2022).
hematologic malignancies (1 paper, 2025). "In the present study, we did not include analyses of MVD, VEGF variants or expression (at the mRNA and protein levels), or other ANGPT2 variants with confirmed significance in hematologic malignancies." (PMID 40115011, 2025).
infectious disease (1 paper, 2014). A disorder directly resulting from the presence and activity of a microbial, viral, or parasitic agent in humans. "Angiogenic factors such as angiopoietin 1 (Ang-1) and angiopoietin 2 (Ang-2) are biomarkers produced during activation and dysfunction of the vascular endothelium in several infectious diseases." (PMID 25275496, 2014). "Angiogenic factors such as angiopoietin 1 (Ang-1) and angiopoietin 2 (Ang-2) are biomarkers produced during activation and dysfunction of the vascular endothelium in non-infectious as well as infectious diseases, including malaria." (PMID 25275496, 2014).
neurodegenerative disease (1 paper, 2024). A disorder of the central nervous system characterized by gradual and progressive loss of neural tissue and neurologic function. "The PPI network analysis showed that Ngfr directly interacts with genes associated with neurodegenerative diseases, such as Bmp4, Ngf, and Angpt2." (PMID 38396669, 2024).
psychiatric disorder (1 paper, 2017). A disorder characterized by behavioral and/or psychological abnormalities, often accompanied by physical symptoms. "Ten genes were enrichedwith several KEGG pathways, and ROBO2, CXCL2, EPHA5,EPHA6, ANGPT2, FGF10, GHF genes was found to be enrichedwith pathways influencing psychiatric disorders like Axonguidance, RAP1 Signaling pathways, RAS Signaling pathwaysetc." (PMID 28539732, 2017).
ANGPT2 also shares sentences with these, for which no sentence is quoted: metastatic melanoma (4 papers); non-small cell lung carcinoma (4); peripheral artery disease (4); retinopathy (4); Alzheimer disease (3); hepatitis C (3); lupus nephritis (3); septic shock (3); systemic lupus erythematosus (3); vasculitis (3); adenoma (2); aortic aneurysm (2); arterial inflammation (2); cholangiocarcinoma (2); infertile (2); lung adenocarcinoma (2); lymphopenia (2); multiple myeloma (2); nephrotic syndrome (2); pancreatitis (2); polymyalgia rheumatica (2); pulmonary embolism (2); Thrombocytopenia (2); Thrombosis (2); type 1 diabetes (2); abdominal aortic aneurysm (1); acute liver failure (1); acute lymphocytic leukemia (1); acute myeloid leukaemia (1); acute-on-chronic liver failure (1).
A further 89 diseases each share a sentence with ANGPT2 in 1 paper.